ZNF761 (zinc finger protein 761)
Description:
May be involved in transcriptional regulation.
Synonyms: KIAA2033; FLJ16231; FLJ35333
Tractability: PROTAC: UniProt records ubiquitination sites on it; ubiquitination databases record sites on it.
Gene: Protein-coding gene on chromosome 19 (53,426,180 to 53,461,862, forward strand). Ensembl gene ENSG00000160336.
Subcellular location: Nucleus
Pathways (Reactome):
Gene expression (Transcription): Generic Transcription Pathway
Gene Ontology:
Molecular function: DNA-binding transcription factor activity, RNA polymerase II-specific; RNA polymerase II cis-regulatory region sequence-specific DNA binding; sequence-specific double-stranded DNA binding
Biological process: regulation of transcription by RNA polymerase II; regulation of DNA-templated transcription
Cellular component: nucleus
Genetic constraint (gnomAD): Loss-of-function variants: 41 observed, 59.38 expected, observed/expected ratio (o/e) 0.69, 90% interval 0.54 to 0.9. The upper end of that interval is the gene's LOEUF score, 0.9, which puts it in group 3 of 6, group 1 being the genes least tolerant of losing a copy. Missense variants: 804 observed, 883 expected, observed/expected ratio (o/e) 0.91, 90% interval 0.86 to 0.96. Synonymous variants: 279 observed, 289.61 expected, observed/expected ratio (o/e) 0.96, 90% interval 0.87 to 1.06.
Homologues: Orthologues: chimpanzee ZNF761 (98% identical). Paralogues in human: ZNF813 (64% identical), ZNF888 (58% identical), ZNF765 (56% identical), ZNF816 (56% identical), ZNF860 (55% identical), ZNF578 (52% identical), ZNF468 (50% identical), ZNF525 (50% identical), ZNF701 (45% identical), ZNF766 (33% identical).
Diseases named in the same sentence as ZNF761 in open-access papers:
ZNF761 is named in the same sentence as 1 disease in open-access papers, as found by Europe PMC text mining. Sharing a sentence is not in itself a finding about the gene and the disease.
ZNF761 shares sentences with these, for which no sentence is quoted: cancer (2 papers).